RIPK3 (receptor interacting serine/threonine kinase 3)
Diseases named in the same sentence as RIPK3 in open-access papers (continued):
Sharing a sentence is not in itself a finding about the gene and the disease.
Hepatic steatosis (11 papers, 2021 to 2025). Steatosis is a term used to denote lipid accumulation within hepatocytes. "We identified the importance of necroptosis in severe hepatic steatosis through loss-of-function of hepatocellular RIPK3." (PMID 36690638, 2023). "In MCD (methionine and choline-deficient) diet-induced mouse model of NAFLD, RIPK3 deficiency reduces liver steatosis, liver inflammation and fibrosis, preventing liver injury." (PMID 39872161, 2022). "Given that TNFα leads to RIPK3 activation and necroptosis induction, which increases inflammation and TNFα levels, ATF3-dependent induction of RIPK3 in severe hepatic steatosis can cause a vicious cycle of necroptosis and inflammation." (PMID 36690638, 2023). "In severe hepatic steatosis, after partial hepatectomy, hepatic ATF3-deficient or -overexpressing mice display decreased or increased RIPK3 expression and necroptosis, respectively." (PMID 36690638, 2023). "The correlation between RIPK3 and hepatic steatosis is well established, and RIPK1/MLKL axis appears to be a considerable pathway of hepatic lipid deposition." (PMID 35083817, 2022). "RIPK3 has been indicated to be a lipid metabolism regulator, differentially controlling liver steatosis." (PMID 35083817, 2022). "In CDAA (choline-deficient l-amino acid-defined) diet-induced mouse model of NAFLD, RIPK3 deletion ameliorates liver inflammation and fibrosis but increases liver steatosis." (PMID 39872161, 2022). "Both MLKL and RIPK3 are promising therapeutic targets to inhibit necroptosis during ischaemic injury in fatty liver." (PMID 33435617, 2021). "Indeed, inhibition of the eIF2α signalling pathway by overexpression of GADD34, a phosphatase of eIF2α, decreased the expression of ATF3 and RIPK3 after resection of severe hepatic steatosis." (PMID 36690638, 2023). "While ATF3 is the inducer of RIPK3, TNFα is a vital activator of RIPK3 in hepatic steatosis." (PMID 36690638, 2023). "Whereas, with increased hepatic steatosis, the transcription factor ATF3 also increases hepatocyte death by inducing RIPK3 expression and changing the TNFα-dependent cell death pattern from apoptosis to necroptosis." (PMID 39244571, 2024). "Both ATF3 and RIPK3 expression are low before hepatectomy in HFD-fed mice, even with severe hepatic steatosis induced by 16 weeks of feeding." (PMID 36690638, 2023). "We found that the mode of hepatocellular death shifts from apoptosis to necroptosis as the hepatic steatosis is exacerbated and that the eIF2α signalling-inducing transcription factor ATF3 determines this modal shift through RIPK3 induction." (PMID 36690638, 2023). "Accumulating evidence illustrated the relevance of key necroptosis signalling molecules including RIPK3 and MLKL, and hepatic steatosis." (PMID 35083817, 2022). "We also revealed that this ATF3-dependent RIPK3 induction plays an important role in the pathogenesis not only of post-hepatectomy acute liver damage in hepatic steatosis but also of chronic liver damage in MCD-fed NASH mice and in patients with NASH." (PMID 36690638, 2023). "Next, we induced hepatocellular ATF3 overexpression in mice with severe hepatic steatosis without hepatectomy to examine the role of ATF3 in RIPK3 expression and necroptosis." (PMID 36690638, 2023). "In this study, we elucidated that ATF3 is the inducer of RIPK3, but not the activator, and the determinant of the modal shift from apoptosis to necroptosis in severe hepatic steatosis." (PMID 36690638, 2023). "Liver steatosis was stimulated after HFD in wild‐type mice, which was aggravated in RIPK3−/− mice." (PMID 35083817, 2022). "Thus, the absence of Mlkl or Ripk3 protects mice against age-related MASLD/MASH pathology by reducing liver steatosis, fibrosis, and liver injury." (PMID 39930289, 2025).
Hepatitis (11 papers, 2015 to 2025). Inflammation of the liver. "The present study suggests that cCK18, CK18, and RIPK3 are associated with the severity of hepatitis." (PMID 37640752, 2023). "The present study suggests that CK18, cCK18, and RIPK3, markers of cell death, are associated with hepatitis severity and MELD in a small number of cases." (PMID 37640752, 2023). "In this study, we revealed that disruption of macrophage Notch1 activated the TAK1-mediated inflammatory responses and RIPK3-mediated hepatocyte necroptosis through activation of β-catenin in IR stress-induced liver inflammation." (PMID 36114543, 2022). "Our results highlight the importance of the macrophage RIPK3-mediated XBP1–Foxo1–Zc3h15 signalling as a critical regulator of the NOD1 and calcineurin/TRPM7 function in IR-triggered liver inflammation." (PMID 37841640, 2023). "HGF was found to be well correlated with the severity of hepatitis and its prognosis in this study, with the group with high HGF and high RIPK3 having a high probability of death." (PMID 37640752, 2023). "Here, we identify a novel regulatory mechanism of macrophage RIPK3 on NOD1 function and the TRPM7-mediated cell death pathway in IR stress-induced liver inflammation." (PMID 37841640, 2023). "MLKL is known to regulate necroptosis during hepatitis through signal transducer and activator of transcription 1 rather than via RIPK3." (PMID 37828052, 2023). "The deletion of TNF receptor in MDR2 KO mice (TNFR1 KO/MDR1 KO) aggravates hepatitis and fibrosis, and it is accompanied with increased RIPK3 but not pMLKL." (PMID 33353156, 2020).
inflammatory bowel disease (11 papers, 2015 to 2025). A spectrum of small and large bowel inflammatory diseases of unknown etiology. "In this regard, it is interesting to note that elevated RIPK3 expression was detected in human patients of inflammatory bowel diseases." (PMID 27446921, 2016). "We found that RIPK3 expression is reduced in tumors from patients with inflammatory bowel diseases, and further confirmed that expression of RIPK3 is downregulated in human CRC and correlated with cancer progression." (PMID 27344176, 2016). "This suggests that RIPK3 may similarly drive inflammatory cytokine expression in human inflammatory bowel diseases." (PMID 27446921, 2016). "Deletion or mutation of Zα residues in ZBP1 confirm a central role for the Z-conformation in RIPK3-dependent necroptosis that occurs in inflammatory bowel disease (IBD), dermatitis and influenza virus infection." (PMID 32742689, 2020). "In inflammatory bowel disease, ATG16L1 has been shown to inhibit RIPK3-dependent necroptosis, thereby activating mitophagy, maintaining mitochondrial integrity, and reducing inflammation." (PMID 41567193, 2025). "Furthermore, we present robust protocols for detecting human Caspase-8, RIPK1, RIPK3, and MLKL and illustrate their utility for detecting dysregulated necroptosis in biopsies from patients with inflammatory bowel disease (IBD)." (PMID 38750308, 2024).
liver diseases (11 papers, 2016 to 2025). "Our results further demonstrate that the same choleretic bile acids (TCA, TUDCA) can induce necroptosis in hepatocytes in various liver diseases associated with hepatocellular RIPK3 expression." (PMID 37072399, 2023). "At the same time, liver-specific knockout of Ripk3 has been shown to attenuate liver damage and inflammation in some models of liver disease models." (PMID 37828052, 2023). "Our findings underscore a novel role of macrophage RIPK3 in stress-induced liver inflammation and cell death, implying the potential therapeutic targets in liver inflammatory diseases." (PMID 37841640, 2023). "This reveals a novel pathophysiological mechanism in the progression of liver diseases, with RIPK3 expression as a molecular switch determining the hepatocyte’s fate." (PMID 37072399, 2023). "On the other hand, it is increasingly noted that RIPK3 is epigenetically silenced in primary hepatocytes in multiple liver disease models and prevents MLKL-mediated cell necroptosis." (PMID 36650126, 2023). "Under basal conditions, RIPK3 is undetectable in liver cells, and its induction is controversial; therefore, the role of necroptosis in hepatocyte cell death in liver diseases is under extensive investigation." (PMID 33353156, 2020). "Afonso and colleagues have also suggested that RIPK3 expression increases in many forms of liver diseases, including hepatitis B, hepatitis C, alcoholic steatohepatitis, and NASH." (PMID 33353156, 2020). "In our present study, elevated, circulating, and hepatic RIPK3 were correlated with the severity of HBV-related liver diseases, i.e., 90-day mortality." (PMID 32655398, 2020). "This study was intrigued by the discrepancy in the role of RIPK3 in hepatic diseases." (PMID 36650126, 2023). "Although we did not observe any protective effects of RIPK3 deficiency in these ALF models, RIPK1-MLKL-mediated necroptosis independently of RIPK3 had been implicated in other liver diseases." (PMID 35853848, 2022). "The predictive accuracy of serum RIPK3 at the 90-day outcome was relatively good with an area under the receiver operating curve (AUROC) of 0.72 (p < 0.001), similar to that of the model of end-staged liver disease (MELD) score (0.76, p < 0.001)." (PMID 32655398, 2020). "Serum RIPK3 was also correlated with a severity score of liver disease, MELD score including its parameters TB and INR, but not with serum creatinine (p < 0.05)." (PMID 32655398, 2020). "However, there is a controversial report on necroptosis in liver diseases, showing that RIPK3 is minimally expressed in the damaged hepatocytes and is not indispensable for the activation of hepatocyte necroptosis." (PMID 32655398, 2020).
psoriasis (11 papers, 2020 to 2025). An autoimmune condition characterized by red, well-delineated plaques with silvery scales that are usually on the extensor surfaces and scalp. "Activation of the RIPK3–MLKL axis has been observed in some neutrophilic diseases including psoriasis." (PMID 35929827, 2022). "NET formation and associated activation of RIPK3/MLKL has been observed in neutrophil-rich tissue samples from patients with cutaneous vasculitis and psoriasis." (PMID 35929827, 2022). "Despite genetic evidence that the IAPs and RIPK1 can repress inflammatory skin lesions, studies into RIPK1 and RIPK3 function in the context of psoriasis are limited." (PMID 33924766, 2021). "Necroptosis, a form of regulated necrosis mediated by receptor-interacting protein kinase 1 (RIPK1), RIPK3, and mixed-lineage kinase domain-like pseudokinase (MLKL), plays a central role in the inflammatory cascade of psoriasis and is also implicated in other inflammatory diseases." (PMID 40906403, 2025). "The heightened expression of necroptosis-associated molecules such as RIPK1 and RIPK3, along with the activation of necroptosis facilitated by the RIPK1/RIPK3 pathway, significantly contribute to the upregulation of IL-17, thereby inducing chronic inflammation in psoriasis." (PMID 39480805, 2024). "Similarly, there was significant up-regulation of RIPK1 and RIPK3 in psoriasis tissues compared to normal samples." (PMID 32075957, 2020). "Although increased expression of pRIPK1 and RIPK3 in the epidermis of human psoriasis samples compared to nonlesional skin has been observed by immunohistochemistry, there is a lack of convincing evidence supporting the activity of necroptosis in human psoriasis." (PMID 32075957, 2020). "However, RIPK3 has been found to promote neutrophil recruitment by inducing cytokine and chemokine expression in keratinocytes in a necroptosis-independent manner, thereby mediating psoriasis inflammation in mice." (PMID 32075957, 2020). "In isolated psoriasis neutrophils, RIPK1 and caspase-8 mRNA were downregulated while RIPK3 and MLKL mRNA were elevated, suggesting enhanced RIPK3/ZBP1-mediated necroptosis." (PMID 41019071, 2025). "In psoriasis, S. aureus infection can also be mediated by the RIPK1/RIPK3/MLKL-mediated necrotizing apoptosis of keratinocytes, and RIPK1 mediates keratinocyte death via TNF." (PMID 35878202, 2022). "Further, the pharmacological inhibition of RIPK1 and RIPK3 through Nec-1s and NSA, respectively, confirmed the role of necroptosis in inflammatory cascades in both in vitro and in vivo psoriasis models." (PMID 36361505, 2022). "Importantly, the hallmarks of necroptosis, such as phosphorylation of RIPK3 and MLKL were significantly increased in the epidermis of human psoriasis lesions." (PMID 38331847, 2024).
ovarian carcinoma (10 papers, 2014 to 2024). A malignant neoplasm originating from the surface ovarian epithelium. "To evaluate whether a functional necrosome complex was indeed forming, we next immunoprecipitated RIPK3 expressed in the ovarian cancer cells and tested for the presence of associated proteins." (PMID 25356865, 2014). "The induction of necroptosis was observed in ovarian cancer and the expression of catalytically active RIPK3 (receptor-interacting protein kinase-3) was necessary for death." (PMID 36357839, 2022). "We found that RIPK3 mRNA levels were progressively lost during tumor growth in colorectal, gastric, and ovarian cancer patients." (PMID 30157175, 2018). "We demonstrate that TNFα production is required to trigger necroptosis in the ovarian cancer cells, and that RIPK3 enhanced this process." (PMID 25356865, 2014). "TNFα appeared to be required for death, as a TNFα-neutralizing antibody was able to rescue cell survival in ovarian carcinomas expressing endogenous or ectopic RIPK3." (PMID 25356865, 2014). "Although RIPK3 expression promotes necroptosis, we only noted the expression of RIPK3 in a few ovarian cancer cell lines." (PMID 25356865, 2014). "We first investigated the expression of RIPK1, RIPK3, caspase-8 and MLKL in a panel of ovarian cancer cell lines as well as HeLa cells." (PMID 29238045, 2017). "RIPK3 exhibits reduced expression levels in the majority of cancers, with the exception of Glioblastoma (GBM), Ovarian Cancer (OV), pancreatic adenocarcinoma (PAAD), and cholangiocarcinoma (CHOL), where it demonstrates elevated expression levels compared to their respective normal tissues." (PMID 38164277, 2024). "This was demonstrated by a greater expression and activation of caspase 3 and 8, RIPK3 (Receptor Interacting Serine/Threonine Kinase 3) and MLKL (Mixed Lineage Kinase Domain Like Pseudokinase), in OVCAR3 and three primary ovarian cancer cell lines derived from patients." (PMID 35669542, 2022). "The induction of necroptosis was common in ovarian cancer, with expression of catalytically active receptor-interacting protein kinase-3 (RIPK3) necessary for death, and in fact sufficient to compromise survival of RIPK3-negative, necroptosis-resistant ovarian cancer cells." (PMID 25356865, 2014). "By contrast, the knockdown of the adaptor protein FADD had a more modest effect, suggesting that FADD may provide some facilitating role in necroptosis in the ovarian cancer cells, yet was not critical in facilitating RIPK1 to RIPK3 signaling." (PMID 25356865, 2014).
Stroke (10 papers, 2018 to 2025). Sudden impairment of blood flow to a part of the brain due to occlusion or rupture of an artery to the brain. "RIPK3 contributes to cell death and neurological dysfunction in Gaucher’s disease and stroke models, and RIPK3 knock out (RIPK3−/−) was associated with reduced post-injury cognitive dysfunction in a controlled cortical impact (CCI) model." (PMID 34753914, 2021). "This study may not only reveal the association of RIPK1 and RIPK3 with stroke severity and prognosis but also explore how these findings can be translated into clinical applications." (PMID 39657719, 2024). "Therefore, serum RIPK1 and RIPK3 levels can reflect the severity of inflammation expression and the severity of the condition after stroke." (PMID 39657719, 2024). "From this, it could be seen that serum RIPK1 and RIPK3 had high predictive value in the assessment of the condition and prognosis of stroke." (PMID 39657719, 2024). "Although the role of RIPK1 and RIPK3 in the regulation of apoptotic signaling has been extensively studied, this study may delve deeper into the specific correlation between RIPK1 and RIPK3 and specific levels in the serum of stroke patients." (PMID 39657719, 2024). "In addition, we propose new diagnostic methods, prognostic assessment tools, or treatment strategies based on RIPK1 and RIPK3 levels that have the potential to bring practical medical benefits to stroke patients." (PMID 39657719, 2024). "Interestingly, the levels of RIPK1 and RIPK3 are reduced after controlling post-traumatic body temperature at 33 °C to reduce brain injury after stroke and TBI." (PMID 36934132, 2023). "Furthermore, inflammation is also a pathologic change that occurs after a stroke, the activity of RIPK1 and RIPK3 is associated with the activation of inflammatory‐related signal pathways in acute ischemic stroke." (PMID 34977874, 2021). "Also, we showed that Ripk3 and Mlkl levels were up-regulated following stroke and reduced by the proliferation-supporting medium, but their high expression levels were maintained by NCS." (PMID 30394012, 2018). "Ripk3 and Mlkl in the ipsilateral hemisphere followed the same expression pattern: they were significantly increased by stroke (P < 0.01 for Ripk3 and P < 0.001 for Mlkl) and reduced by the injection of proliferation-supporting medium (significant for Mlkl P < 0.01), but not by NSC transplantation." (PMID 30394012, 2018). "On the other hand, RIPK3-deficient mice were not protected against tMCAO-induced stroke compared with their wild type counterparts." (PMID 30394012, 2018). "For example, we showed that Casp8, Ripk1, and Ripk3 were up-regulated following stroke, although it has been shown that CASP8 blocks assembly of necroptotic complex composed of RIPK1 and RIPK3, leading the cell to apoptosis." (PMID 30394012, 2018).